LINC00051 (long independently transcribed non-coding RNA 51)
Synonyms: C8orf43; NCRNA00051
Gene: Long non-coding RNA gene on chromosome 8 (142,198,319 to 142,209,003, forward strand). Ensembl gene ENSG00000254008.
Diseases named in the same sentence as LINC00051 in open-access papers:
LINC00051 is named in the same sentence as 1 disease in open-access papers, as found by Europe PMC text mining. Sharing a sentence is not in itself a finding about the gene and the disease. The quoted sentences say what the papers report.
bladder cancer (1 paper, 2020). "A comprehensive analysis of bladder cancer microarray data GSE61615 revealed 4 significant differential LincRNAs, LINC00051, LINC00116, LINC00338 and LINC00482, where logFC of LINC00482 was the highest." (PMID 33323547, 2020).